LCN6 (lipocalin 6)
Description:
May play a role in male fertility.
Synonyms: LCN5; UNQ643; hLcn5
Tractability: Antibody: UniProt places it where antibodies can reach, with medium confidence; UniProt predicts a signal peptide or a membrane-spanning region; its Gene Ontology location is reachable by antibodies, with medium confidence.
Gene: Protein-coding gene on chromosome 9 (136,744,017 to 136,748,525, reverse strand). Ensembl gene ENSG00000267206.
Subcellular location: Secreted
Gene Ontology:
Molecular function: small molecule binding
Cellular component: extracellular region
Genetic constraint (gnomAD): Loss-of-function variants: 18 observed, 21.19 expected, observed/expected ratio (o/e) 0.85, 90% interval 0.59 to 1.26. The upper end of that interval is the gene's LOEUF score, 1.26, which puts it in group 5 of 6, group 1 being the genes least tolerant of losing a copy. Missense variants: 217 observed, 213.88 expected, observed/expected ratio (o/e) 1.01, 90% interval 0.91 to 1.13. Synonymous variants: 96 observed, 92.29 expected, observed/expected ratio (o/e) 1.04, 90% interval 0.88 to 1.23.
Homologues: Orthologues: macaque LCN6 (90% identical), mouse Lcn6 (73% identical), dog LCN6 (71% identical), rat Lcn6 (71% identical), guinea pig LCN6 (70% identical), pig LCN6 (67% identical). Paralogues in human: LCN15 (26% identical), LCN10 (25% identical), LCN2 (22% identical), PTGDS (22% identical), LCN1 (20% identical), OBP2A (20% identical), OBP2B (20% identical), LCN9 (18% identical), LCN12 (17% identical), LCN8 (16% identical), PAEP (15% identical), LCNL1 (13% identical).
Diseases named in the same sentence as LCN6 in open-access papers:
LCN6 is named in the same sentence as 5 diseases in open-access papers, as found by Europe PMC text mining. Sharing a sentence is not in itself a finding about the gene and the disease. The quoted sentences say what the papers report.
epithelial ovarian cancer (2 papers, 2021 to 2023). "Scientific literature is currently limited on the biology of Lipocalin 6 (LCN6), but it was recently identified as one of a panel of nine immune-related genes able to predict overall survival class of epithelial ovarian cancer patients as “low-risk” or “high-risk”." (PMID 37435088, 2023).
heart failure (1 paper, 2020). Inability of the heart to pump blood at an adequate rate to meet tissue metabolic requirements. "Using existing gene expression data in the Gene Expression Omnibus (GEO) database, we screened differentially expressed genes (DEGs) of heart failure and identified six key genes (HMOX2, SERPINA3, LCN6, CSDC2, FREM1, and ZMAT1) by random forest classifier." (PMID 33401250, 2020).
Sleep apnea (1 paper, 2017). An intermittent cessation of airflow at the mouth and nose during sleep is known as sleep apnea. "Suggestive associations of symptoms of sleep apnea were observed with 11 rare variants (located in KANK2, LCN6, TRAF3, PLEK, HIF1A, SLC45A3, ERCC1/CD3EAP, MRGPRE, GRAMD4, TYW5, CST5)." (PMID 29093733, 2017).
LCN6 also shares sentences with these, for which no sentence is quoted: cancer (1 paper); ovarian cancer (1).